POU4F3 (POU class 4 homeobox 3)
Description:
Acts as a transcriptional activator. Acts by binding to sequences related to the consensus octamer motif 5'-ATGCAAAT-3' in the regulatory regions of its target genes. Involved in the auditory system development, required for terminal differentiation of hair cells in the inner ear (By similarity).
Synonyms: BRN3C; DFNA15; DFNA42; DFNA52
Tractability: No criterion of Open Targets' tractability assessment is met for any kind of drug.
Gene: Protein-coding gene on chromosome 5 (146,338,648 to 146,341,728, forward strand). Ensembl gene ENSG00000091010.
Subcellular location: Nucleus; Cytoplasm
Subcellular location (Human Protein Atlas): Nucleoplasm
Gene Ontology:
Molecular function: DNA-binding transcription activator activity, RNA polymerase II-specific; protein binding; RNA polymerase II cis-regulatory region sequence-specific DNA binding; sequence-specific double-stranded DNA binding; DNA-binding transcription factor activity; DNA-binding transcription factor activity, RNA polymerase II-specific; DNA binding; sequence-specific DNA binding
Biological process: positive regulation of transcription by RNA polymerase II; regulation of transcription by RNA polymerase II; sensory perception of sound; visual perception; regulation of DNA-templated transcription
Cellular component: cytoplasm; nucleoplasm; nucleus; chromatin; RNA polymerase II transcription regulator complex
Genetic constraint (gnomAD): Loss-of-function variants: 7 observed, 23.28 expected, observed/expected ratio (o/e) 0.3, 90% interval 0.17 to 0.56. The upper end of that interval is the gene's LOEUF score, 0.56, which puts it in group 2 of 6, group 1 being the genes least tolerant of losing a copy. Missense variants: 457 observed, 494.16 expected, observed/expected ratio (o/e) 0.92, 90% interval 0.86 to 1. Synonymous variants: 220 observed, 209.32 expected, observed/expected ratio (o/e) 1.05, 90% interval 0.94 to 1.17.
Gene-disease validity (ClinGen):
ClinGen rates the evidence that POU4F3 causes each of these diseases.
nonsyndromic genetic hearing loss (autosomal dominant): Definitive.
Homologues: Orthologues: chimpanzee POU4F3 (100% identical), pig POU4F3 (99% identical), dog POU4F3 (99% identical), guinea pig POU4F3 (99% identical), mouse Pou4f3 (99% identical), rat Pou4f3 (99% identical), tropical clawed frog pou4f3 (87% identical), zebrafish pou4f3 (83% identical), Drosophila melanogaster acj6 (56% identical), Caenorhabditis elegans unc-86 (46% identical), Caenorhabditis elegans ceh-18 (31% identical), Drosophila melanogaster vvl (29% identical). Paralogues in human: POU4F2 (74% identical), POU4F1 (73% identical), POU2F1 (33% identical), POU3F3 (32% identical), POU3F2 (32% identical), POU3F4 (32% identical), POU2F2 (31% identical), POU2F3 (30% identical), POU1F1 (29% identical), POU3F1 (29% identical), POU5F1 (28% identical), POU5F1B (27% identical), and 5 more.
Diseases named in the same sentence as POU4F3 in open-access papers:
POU4F3 is named in the same sentence as 29 diseases in open-access papers, as found by Europe PMC text mining. Sharing a sentence is not in itself a finding about the gene and the disease. The quoted sentences say what the papers report.
hearing loss (27 papers, 2010 to 2024). "Patients with DFNA15, who have one normal copy of Pou4f3, are born with normal hearing, and experience progressive hearing loss with different ages of onset, most commonly occurring after adolescence." (PMID 38566840, 2024). "Of note, this person has hearing loss, and POU4F3 has an established relationship with hearing loss; in addition, ATP2B2 has been implicated in hearing loss." (PMID 38674358, 2024). "Collectively, the results provide evidence that patient-derived LCLs can be implicated in the transcriptome study of genetic hearing loss for studying POU4F3 transcriptional function." (PMID 37537203, 2023). "We performed RNA sequencing analysis to investigate comprehensively the molecular pathways affected by POU4F3 variants identified from the hearing-loss families." (PMID 37537203, 2023). "Previous studies suggested that POU4F3 is one of the signature gene associated with mid-frequency hearing loss, showing a down-sloping configuration over time." (PMID 37537203, 2023). "As such, our study's findings demonstrate that patient-derived LCLs can be effectively utilized in transcriptome studies of genetic hearing loss to investigate POU4F3 transcriptional function." (PMID 37537203, 2023). "Even though marginal, quantitative analyses reached statistical significance, suggesting the POU4F3 variant regulates MYO6 expression in the hearing loss pathology." (PMID 37537203, 2023). "The conclusions of this paper will add insight into the growing knowledge of information on the pathogenesis of POU4F3-associated hearing loss." (PMID 34250087, 2021). "Since mutation of POU4F3 was first discovered as a pathogenic cause for hearing loss in 1998,12 scientist and clinicians have identified 28 variants in POU4F3 and a complete loss of POU4F3 to be associated with ADNSHL." (PMID 32390314, 2020). "All these reports point to POU4F3 as the candidate DFNA15 gene in patients that suffer this autosomal dominant progressive hearing loss." (PMID 32970669, 2020). "This study provided new knowledge of POU4F3 mutation spectrum associated with hearing loss and helps to identify the pathogenic mechanism of POU4F." (PMID 32390314, 2020). "The age of onset of hearing loss, ranging from the first to fourth decade of life, differs among POU4F3 mutations." (PMID 29850532, 2018). "In the present study, genetic screening for POU4F3 variants was carried out for a large series of Japanese hearing loss (HL) patients to clarify the prevalence and clinical characteristics of DFNA15 in the Japanese population." (PMID 28545070, 2017). "Here, we report the first nonsense mutation of POU4F3 associated with progressive hearing loss and explored the possible underlying mechanism." (PMID 27999687, 2016). "In future studies, therefore, it will be interesting to correlate the presumably reduced levels of the Gfi1 transcription with different POU4F3 mutations and the severity of the associated hearing loss." (PMID 28053790, 2016). "Identification of targets of POU4F3 is important for understanding its function and the mechanism of POU4F3-related hearing loss." (PMID 27999687, 2016). "Although the underlying mechanism is unclear, mutation of POU4F3 causes progressive hearing loss in humans." (PMID 21496241, 2011). "The altered expression of downstream POU4F3 targets identified herein may support the a mechanistic basis for hearing loss caused by POU4F3 variants." (PMID 37537203, 2023). "We characterize all four novel POU4F3 variants functionally via computational structural modeling and functional studies, revealing diverse pathogenic mechanisms underlying POU4F3-associated hearing loss." (PMID 37537203, 2023).
hearing loss (continued). "The reduced nuclear presence, combined with reduced transcriptional activity, suggests that the POU4F3 c.602T>C variant alters cellular activity and may contribute to the pathogenicity of POU4F3-related hearing loss." (PMID 34250087, 2021). "In addition, studies showed that the pathways downstream of POU4F3 play crucial roles in the maintenance of inner ear hair cells, which also provides insight into the mechanisms underlying POU4F3 mutation-induced hearing loss." (PMID 32684921, 2020). "Although the pathogenic mechanisms underlying hearing impairment of patients with POU4F3 variants remain unclear, the mechanism of haploinsufficiency has been supported by several studies." (PMID 29850532, 2018). "The vital role of POU4F3 in the development of hair cells indicated that it might be related with some kind of hereditary hearing loss." (PMID 27999687, 2016). "Based on their continuous expression in adult RGCs and the similarity in structure and function of all POU4F members, we hypothesized that like the mutation of POU4F3 results in the hearing loss, loss of POU4F function may affect the survival of adult RGCs." (PMID 24736625, 2014). "The results of gene expression analysis of each cochlear turn showed that 4 ADNSHL genes (Pou4f3, Slc17a8, Tmc1, and Crym) and 9 autosomal recessive non syndromic hearing loss genes (Otof, Strc, Ush1c, Pcdh15, Grxcr1, Dfnb59, Slc26a5, Lhfpl5, and Ptprq) were changed 2-fold or more." (PMID 24676347, 2014). "Such an understanding may also aid in the explanation of the mechanism by which POU4F3 mutation causes hearing loss in humans." (PMID 25372459, 2014). "Thus, hearing loss could be caused by insufficient levels of POU4F3 or interference of the mutant protein with the normal POU4F3, impacting protein function, stability, cellular localization, or DNA binding." (PMID 38566840, 2024). "Therefore, upregulation of Pou4f3 by DEAB or other RA antagonists (e.g. BMS195614) may also provide therapeutic potential for treatment of other types of hearing loss." (PMID 32970669, 2020). "This is the first report of mutations in ACTG1, POU4F3, and SLC26A5 in Japanese families with hearing loss." (PMID 24164807, 2013). "The gene POU4F3 (Brn3c) is specifically expressed in hair-cells and mutations in POU4F3 causes DFNA15, an autosomal dominant form of progressive hearing loss." (PMID 21209840, 2010). "We concluded that the POU4F3 variations might regulate Wnt, Notch, and/or BMP pathways, specifically leading to the misregulation of BMP2, MYO6, and AHI1 in the pathogenesis of hearing loss." (PMID 37537203, 2023). "POU4F3 might be a candidate for hereditary hearing impairment because of its important role in hair cells." (PMID 32390314, 2020). "POU4F3 – a POU-domain transcription factor selectively expressed by these cells – has been shown to be essential for hair cell differentiation and survival in mice and its mutation in humans underlies late-onset progressive hearing loss (DFNA15)." (PMID 25372459, 2014). "Thus, while our work shows the importance of Pou4f3 in regulating the survival and maintenance of mouse cochlear HCs at postnatal and adult ages, there is still much to learn in understanding the mechanism of DFNA15-induced hearing loss." (PMID 38566840, 2024). "Genetic screening for Pou4f3 variants in a Japanese population demonstrated that individuals with mutations that produce a truncated POU4F3 showed earlier onset and slower progression of hearing loss than patients carrying different non-truncating mutations in Pou4f3." (PMID 38566840, 2024). "For most family members inheriting one copy of POU4F3 c.37del, the exact age of hearing loss onset could not be confirmed audiometrically, given that hearing loss was present on the first audiogram acquired during adulthood." (PMID 37072551, 2023).
hearing loss (continued). "Moreover, it was reported that patients with truncated POU4F3 variants exhibited earlier onset, but slow progression of hearing loss, relative to patients with nontruncated variants." (PMID 34250087, 2021). "Pou4f3 is a transcription factor implicated in progressive non-syndromic hearing loss in humans." (PMID 29073148, 2017). "Mutation of POU4F3 may not be a rare cause in ADNSHL and routine examination of POU4F3 is necessary for the genetic diagnosis of hereditary hearing loss in the future." (PMID 27999687, 2016). "However, in this NA kindred, ARTAs predicting early mid-frequency hearing impairment do not reflect the natural course for POU4F3 c.37del carriers experiencing later onset and other audiogram configurations." (PMID 37072551, 2023).
deafness (18 papers, 2013 to 2025). An inherited or acquired condition characterized by the complete loss of the ability to hear from one or both ears. "The second is a missense variant in POU4F3 which is reported to have associations with deafness: autosomal dominant 15 (MIM# 602459)." (PMID 38674358, 2024). "The results of this study suggest that POU4F3 is the most common TF gene to cause non-syndromic deafness, excluding POU3F4 associated with X-linked inherited deafness in IP type III." (PMID 36140227, 2022). "In humans, POU4F3 defects commonly cause autosomal dominant deafness, with variants associated with progressive non-syndromic deafness of postlingual onset." (PMID 36140227, 2022). "Our results also indicate that the onset of DFNA15 deafness is modified by genetic and environment factors and that POU4F3 haploinsufficiency is the main underlying cause of DFNA15 deafness." (PMID 32970669, 2020). "In this study, we established a novel mouse model of the human DFNA15 deafness, with a Pou4f3 gene mutation (Pou4f3Δ) identical to that found in a familial case of DFNA15." (PMID 32970669, 2020). "By combining targeted capture of 129 known deafness genes, next-generation sequencing, and bioinformatic analysis, we identified POU4F3 c.602T>C (p.Leu201Pro) as the disease-causing variant." (PMID 29850532, 2018). "Targeted deletion of both alleles of Pou4f3 is responsible for profound deafness and balance impairment in mice because of complete cochlear and vestibular hair cell losses followed by a partial secondary loss of spiral and vestibular ganglion neurons." (PMID 28545070, 2017). "In other words, variants in POU4F3 are a rare cause of deafness from an epidemiological perspective." (PMID 28790396, 2017). "Using a massively parallel sequencing panel targeting 159 deafness genes, we identified a novel missense variant of POU4F3 (c.982A>G, p.Lys328Glu) which co-segregated with the deafness phenotype in a three-generation Taiwanese family with ADNSHL." (PMID 28790396, 2017). "Combined with our present and previous studies, we identified mutations in POU4F3 as the pathogenic cause of deafness in 3 of the 16 (18%) Chinese Han ADNSHL families, suggesting that it is a relatively common cause for ADNSHL in Chinese Hans." (PMID 28053790, 2016). "POU4F3 was an excellent candidate gene because targeted deletion of both Pou5f3 alleles in mice had been reported to result in complete deafness." (PMID 24260153, 2013). "The novel mutations of POU4F3 co‐segregated with the deafness phenotype in these two families." (PMID 32390314, 2020). "POU4F3 is the earliest discovered deafness‐related gene to cause ADNSHL DFNA15." (PMID 32390314, 2020). "To determine whether POU4F3 variants cause deafness in other Taiwanese families, we sequenced both exons of POU4F3 in 13 additional unrelated families with ADNSHL by either Sanger sequencing or the MPS panel." (PMID 28790396, 2017). "POU4F3 (MIM #602460) is one of the earliest deafness genes identified to cause ADNSHL DFNA15." (PMID 28790396, 2017). "Firstly, some of the genes are independently known to be involved in hearing, such as Fgf8, Slc26a5 (prestin), Pou4f3 and Gfi19, 10, 39, 40, suggesting that other genes in the network may also underlie deafness." (PMID 26988146, 2016). "POU4F3 (DFNA15) was one of the first deafness genes to be identified in 1998, in an Israeli Jewish kindred where 12 members presented between 18–30 years of age with progressive ADSNHL." (PMID 37072551, 2023). "The two Pou4f3 mouse models allowed us to confirm that DFNA15 deafness is caused by haploinsufficiency in Pou4f3 expression, which then facilitates the identification and modulation of RA signaling for Pou4f3 upregulation and treatment of DFNA15 deafness." (PMID 32970669, 2020). "To address the pathological basis of the DFNA15 deafness, we performed thorough histological analyses in Pou4f3(Δ/+) mice at 4–6 months age." (PMID 32970669, 2020).
deafness (continued). "Among a number of nonsyndromic deafness genes, variants in SLC26A4, COCH, MYO7A, GRHL2, and CLIC5 as well as POU4F3 are known to cause vestibular symptoms and/or dysfunction." (PMID 28545070, 2017). "We performed Sanger sequencing and found POU4F3 c.982A>G co-segregated with the deafness phenotype in the family." (PMID 28790396, 2017). "In the previous (n = 7) and the present (n = 9) studies, we preformed targeted NGS of known deafness genes in 16 Chinese Han ADNSHL families and identified novel mutations in POU4F3 as the pathogenic cause in three of them." (PMID 28053790, 2016). "In the present study, we performed targeted next-generation sequencing of 144 known deafness genes in another nine Chinese Han ADNSHL families and identified two more novel mutations in POU4F3, p.Leu311Pro and c.120+1G>C, as the pathogenic cause." (PMID 28053790, 2016). "Of them, 9 deafness genes expressed more in the apical turn (Pou4f3, Slc17a8, Tmc1, Crym, Otof, Ush1c, Pcdh15, Slc26a5, and Lhfpl5) and six were internal controls (Gapdh, Actb, Rps17, Rpl30, Atp6, and Ipo8)." (PMID 24676347, 2014). "These Pou4f3(Δ/+) mice exhibited progressive deafness similar to that observed in DFNA15 patients." (PMID 41227304, 2025). "A mouse model of human DFNA15 deafness, with a Pou4f3 gene variation, has been engineered." (PMID 41227304, 2025). "Although the mechanism of deafness caused by POU4F3 mutations is not well studied, the results of several studies point to haploinsufficiency." (PMID 32390314, 2020). "The Pou4f3(Δ/+) mice suffered progressive deafness in a similar manner to the DFNA15 patients." (PMID 32970669, 2020). "Moreover, the expression levels of the other nine deafness-related genes (Myo15, Gfi1, Lhx3, Barhl1, Pjvk, Tomt, Pou4f3, Tmc1, and Grxcr2) were downregulated more than 2-fold in DT-treated Prestin-hDTR mice." (PMID 30918314, 2019). "Therefore, POU4F3 is an important deafness gene in autosomal dominant HL patients, particularly in patients with mid- or high-frequency HL." (PMID 28545070, 2017). "Of them, three were novel missense mutations (p.G38D in COCH, p.E316K in ACTG1, and p.P164R in POU4F3), one was a novel in-frame indel mutation (c.2036-2038delAGG in WFS1), and two were known deafness-causing mutations that have been previously reported (p.R653C in WFS1 and p.D572N in TMC1)." (PMID 25388789, 2014). "The precise molecular pathophysiological mechanisms would be different between POU3F4- and POU4F3- related deafness in speculation of the different modes of inheritance (X-linked recessive vs autosomal dominant, respectively)." (PMID 24260153, 2013). "Importantly, deletion of the entire POU4F3 gene has been reported in a DFNA15 deafness family." (PMID 32970669, 2020). "In our study, Aldh inhibitor DEAB administered intraperitoneally daily showed potent effects on Pou4f3 upregulation and rescue of DFNA15 deafness in mice." (PMID 32970669, 2020).